LINC00475 (long independently transcribed non-coding RNA 475)
Synonyms: formerly C9orf44
Gene: Transcribed unprocessed pseudogene on chromosome 9 (92,141,438 to 92,141,650, forward strand). Ensembl gene ENSG00000225511.
Diseases named in the same sentence as LINC00475 in open-access papers:
LINC00475 is named in the same sentence as 9 diseases in open-access papers, as found by Europe PMC text mining. Sharing a sentence is not in itself a finding about the gene and the disease. The quoted sentences say what the papers report.
glioma (7 papers, 2020 to 2024). A benign or malignant brain and spinal cord tumor that arises from glial cells (astrocytes, oligodendrocytes, ependymal cells). "In this study, we aimed to elucidate the underlying mechanisms responsible for the AS of LINC00475 and its induction of mitochondrial fission in glioma." (PMID 38405130, 2024). "LINC00475 was confirmed to be overexpressed and with higher frequencies of AS events in gliomas compared to normal brain tissue and was associated with worse prognosis." (PMID 38405130, 2024). "Recently, linc00475 has been proposed to be associated with the overall survival of glioblastoma multiforme patients, while the underlying molecular mechanisms of linc00475 in glioma remain to be addressed." (PMID 33336871, 2021). "Given the elevated expression of linc00475 in glioma and its association with shorter OS, we further explored the effect of linc00475 in glioma cells." (PMID 33336871, 2021). "Notably, our recent investigation has unveiled the presence of a cleaved variant of LINC00475, which promotes mitochondrial fission in glioma cells." (PMID 38405130, 2024). "To elucidate the mechanism by which METTL3 facilitates LINC00475 splicing in gliomas, we employed pulldown-LC/MS (liquid chromatography/mass spectrometry) to screen proteins that directly interact with LINC00475." (PMID 38405130, 2024). "Mechanistically, METTL3 induced the generation of LINC00475-S by splicing LINC00475 through m6A modification and subsequently promotes mitochondrial fission in glioma cells by inhibiting the expression of MIF." (PMID 38405130, 2024). "A positive correlation between METTL3 and both LINC00475 and LINC00475-S was identified in glioma tissues." (PMID 38405130, 2024). "The highest level of LINC00475-S was exhibited in U251 cells, followed by U87 cells and U138 cells, and LINC00475 was found to be localized in both the cytoplasm and nucleus of glioma cells through nucleocytoplasmic separation experiment." (PMID 38405130, 2024). "To corroborate this discovery, we employed fluorescence in situ hybridization (FISH) to assess the expression of truncated LINC00475 (LINC00475-S, 1,184 nt) and full-length LINC00475 (2,000 nt) in glioma tissues." (PMID 38405130, 2024). "METTL3-dependent m6A methylation enhanced the binding of GYR and GY domains of HNRNPH1 to LINC00475, ultimately promoting glioma progression by inducing mitochondrial fission." (PMID 38405130, 2024). "In conclusion, METTL3-mediated m6A triggered mitochondrial fission by facilitating the binding between HNRNPH1 and LINC00475, thereby promoting glioma progression." (PMID 38405130, 2024). "The expression of LINC00475 and its correlation with clinical parameters in glioma were analyzed using bioinformatics." (PMID 38405130, 2024). "METTL3 facilitated HNRNPH1-mediated AS of LINC00475, which promoted glioma progression by inducing mitochondrial fission." (PMID 38405130, 2024). "Previous studies have proved that LINC00475 expression is up-regulated in glioma and can promote the progression of glioma." (PMID 35359381, 2022). "Our study proved that miR‐141‐3p was expressed at low levels in glioma and was involved in the regulation of linc00475 by acting as a sponge for YAP1." (PMID 33336871, 2021). "Overexpression of LINC00475 was observed in hypoxic gliomas and silencing LINC00475 results in suppression of tumor proliferation, migration, as well as invasion." (PMID 34950662, 2021). "Expectedly, the expression of YAP1 was down‐regulated after knock‐down of linc00475 in glioma cells." (PMID 33336871, 2021). "Then, we detected the expression of linc00475 in a cohort of 40 glioma tissues and glioma cells by qRT‐PCR." (PMID 33336871, 2021). "Here, we analysed the expression levels of linc00475 by qRT‐PCR and discovered that linc00475 was up‐regulated in glioma and predicted a poor prognosis in patients with glioma." (PMID 33336871, 2021).
glioma (continued). "To further confirm the oncogenesis of linc00475 in glioma, we prepared subcutaneous tumour models and orthotopic xenografts." (PMID 33336871, 2021). "As predicted, linc00475 in glioma tissues was observed to be triple the levels of normal brain tissues (NBTs)." (PMID 33336871, 2021). "The rescue assays confirmed that inhibiting linc00475 restrained the progression of glioma through the miR‐141‐3p/YAP1 pathway." (PMID 33336871, 2021). "We globally analysed the change in miRNAs after knock‐down of linc00475 in glioma cells and discovered that miR‐141‐3p increased in sh‐linc00475 glioma cells." (PMID 33336871, 2021). "In the present study, we revealed that linc00475 is amplified in glioma and was correlated with a poor prognosis." (PMID 33336871, 2021). "Further experiments confirmed that linc00475 regulated the progression of glioma by acting as a sponge for miR‐141‐3p." (PMID 33336871, 2021). "Overall, linc00475 was significantly up‐regulated in glioma, and patients with amplified linc00475 had a shorter OS." (PMID 33336871, 2021). "Silencing of LINC00475 suppressed cell proliferation, migration, and invasion in renal cell carcinoma and glioma cells in vitro." (PMID 32149080, 2020). "In this study, the results suggest that AS of LINC00475 may take part in the development and recurrence of glioma." (PMID 38405130, 2024). "However, LINC00475 expression was elevated in high-grade gliomas in patients aged 42 years or older compared to their younger counterparts." (PMID 38405130, 2024). "Notably, the expression of LINC00475 was significantly higher in IDH1 wild-type gliomas compared to IDH1 mutant gliomas." (PMID 38405130, 2024). "As predicted, knock‐down of linc00475 repressed the proliferation of glioma cells." (PMID 33336871, 2021). "Then, we confirmed that high linc00475 expression predicted a poor OS in patients with glioma." (PMID 33336871, 2021). "Knock‐down of linc00475 inhibited tumorigenesis of glioma through the miR‐141‐3p/YAP1 pathway." (PMID 33336871, 2021). "This current study revealed that the expression of linc00475 elevates in glioma." (PMID 33336871, 2021). "We synthesized two target siRNAs to establish the glioma cells with suppressed linc00475." (PMID 33336871, 2021). "Moreover, we discovered that inhibiting linc00475 attenuated tumorigenesis of glioma in vitro and in vivo." (PMID 33336871, 2021). "In addition, we demonstrated that high linc00475 expression predicted shorter survival in patients suffering from glioma." (PMID 33336871, 2021). "We analysed the roles of linc00475 in the biological function of glioma in vitro and in vivo." (PMID 33336871, 2021). "By regulating the miR-141-3p/YAP1 axis, LINC00475 facilitates tumor progression of glioma." (PMID 34950662, 2021). "We performed rescue assays to confirm whether miR‐141‐3p and YAP1 are involved in linc00475‐mediated glioma development." (PMID 33336871, 2021). "Collectively, our research demonstrates the key roles of linc00475 in glioma, which could be a promising therapeutic target." (PMID 33336871, 2021). "Targeting AS of LINC00475 and m6A editing could serve as a therapeutic strategy against gliomas." (PMID 38405130, 2024). "Similarly, sh‐linc00475 significantly limited the migration and invasion ability of glioma cells." (PMID 33336871, 2021). "Besides, inhibiting linc00475 restrained the progression of glioma in vitro and in vivo." (PMID 33336871, 2021). "To elucidate the role of m6A modifiers in regulating AS of LINC00475, we initially assessed the expression levels of METTL3, ALKBH5, and FTO in glioma cells." (PMID 38405130, 2024). "Previously, LINC00475 was reported to be mainly localized in both cytoplasm and nucleus of LN229 cells (glioma)." (PMID 34950770, 2022).
glioma (continued). "Analysis of The Cancer Genome Atlas (TCGA) data revealed a significant up-regulation of LINC00475 expression in recurrent gliomas compared to primary gliomas and normal brain tissues; however, no marked difference was observed between recurrent and primary gliomas from the CGGA data." (PMID 38405130, 2024). "Furthermore, we confirmed a negative correlation between miR‐141‐3p and linc00475 in both sh‐linc00475 and anti‐miR‐141‐3p glioma cells." (PMID 33336871, 2021).
thyroid carcinoma (1 paper, 2022). "According to bioinformatics analysis, LINC00475 is highly expressed in thyroid carcinoma tissue samples (n = 510)." (PMID 34950770, 2022).
cancer (1 paper, 2023). A tumor composed of atypical neoplastic, often pleomorphic cells that invade other tissues.
LINC00475 also shares sentences with these, for which no sentence is quoted: tumour (3 papers); glioblastoma (1); lymphoma (1); ovarian carcinoma (1); renal cell carcinoma (1); renal clear cell sarcoma (1).